SOD1 (superoxide dismutase 1)
Diseases named in the same sentence as SOD1 in open-access papers (continued):
Sharing a sentence is not in itself a finding about the gene and the disease.
amyotrophic lateral sclerosis (continued). "In fact, for instance, SOD enzymes may also be responsible for the occurrence of some diseases, as approximately 20% of the familial cases of Amyotrophic Lateral Sclerosis appear to arise as a consequence of mutations in the copper/zinc superoxide dismutase gene SOD1." (PMID 34948180, 2021). "SOD1 mutations account for ∼20% of familial amyotrophic lateral sclerosis (ALS) cases in which the hallmark pathological feature is insoluble SOD1 aggregates within motor neurons." (PMID 34803609, 2021). "Regarding amyotrophic lateral sclerosis (ALS), mutations of copper-zinc superoxide dismutase (SOD1) are one of the important causes of inherited ALS." (PMID 34531720, 2021). "Mutations in superoxide dismutase 1 (SOD1) cause familial amyotrophic lateral sclerosis (ALS) in humans." (PMID 32994185, 2020). "Pathological forms of TAR DNA-binding protein 43 (TDP-43) are present in almost all cases of amyotrophic lateral sclerosis (ALS), and 20% of familial ALS cases are due to mutations in superoxide dismutase 1 (SOD1)." (PMID 32446203, 2020). "Mutations in DNA/RNA‐binding factor (fused‐in‐sarcoma) FUS and superoxide dismutase‐1 (SOD‐1) cause amyotrophic lateral sclerosis (ALS)." (PMID 31867846, 2020). "On the other hand, the notion that enhanced OS contributes to muscle wasting is also supported by SOD1 inactivating mutations that lead, among other effects, to muscle depletion in animal models and patients with amyotrophic lateral sclerosis (ALS)." (PMID 33255345, 2020). "Aβ oligomers in Alzheimer’s disease, SOD1 mutants in Amyotrophic Lateral Sclerosis (ALS), and α-syn in PD, all associate with the Voltage-Dependent Anion Channels (VDAC) isoform 1, reducing dramatically the mitochondria synthesized ATP availability." (PMID 33105548, 2020). "NMD such as Charcot-Marie-Tooth neuropathy type 2A (CMT2A) or amyotrophic lateral sclerosis (ALS) can also be caused by mitochondrial mutations (CMT2A can be caused by mutations in MFN2 and ALS by mutations in SOD1)." (PMID 33050147, 2020). "About 20% of familial forms of amyotrophic lateral sclerosis (ALS) are characterized by mutations in the superoxide dismutase 1 (SOD1) gene." (PMID 32903427, 2020). "To see whether it extends to other mouse models of neuromuscular disease, we analyzed L1-L5 DRG from SOD1G93A mice, an established model of SOD1-associated amyotrophic lateral sclerosis (ALS), which displays a plethora of defects and dysfunctional pathways in peripheral, albeit mainly motor, nerves." (PMID 32848623, 2020). "Mutations of SOD1 gene have been associated with amyotrophic lateral sclerosis (ALS), also known as Lou Gehrig’s disease." (PMID 32198463, 2020). "Mutations in the copper zinc superoxide dismutase 1 (SOD1) gene are the second most frequent cause of familial amyotrophic lateral sclerosis (ALS)." (PMID 32948071, 2020). "A subset of familial forms of amyotrophic lateral sclerosis (ALS) are caused by mutations in the gene coding Cu/Zn-superoxide dismutase (SOD1)." (PMID 31744522, 2019). "Superoxide dismutase-1 (SOD-1) is a free radical scavenging metalloenzyme that can contain aggregation-prone mutations linked to familial amyotrophic lateral sclerosis (ALS), a neurodegenerative motoneuron disease." (PMID 31619995, 2019). "Mutations in superoxide dismutase (SOD1) are the second most common cause of familial amyotrophic lateral sclerosis (ALS), a fatal neurodegenerative disease caused by the death of motor neurons in the brain and spinal cord." (PMID 31474832, 2019). "Based on similar clinical signs, neuropathological findings, and the involvement of the SOD1 mutation, DM is regarded as a naturally-occurring model of amyotrophic lateral sclerosis (ALS)." (PMID 31182094, 2019). "Accumulation of mutated superoxide dismutase 1 (mSOD1) in amyotrophic lateral sclerosis (ALS) involves injury to motor neurons (MNs), activation of glial cells and immune unbalance." (PMID 31024256, 2019).
amyotrophic lateral sclerosis (continued). "Even within the same disease, in cases like amyotrophic lateral sclerosis (ALS), there is a broad array of mutated genes, such as SOD-1 or SEXT, which result in the same symptomatology by which they are then grouped." (PMID 31723121, 2019). "Motor neurons containing aggregates of superoxide dismutase 1 (SOD1) are hallmarks of amyotrophic lateral sclerosis (ALS) caused by mutations in the gene encoding SOD1." (PMID 30284034, 2018). "Mutations in Cu/Zn superoxide dismutase 1 (SOD1) lead to Amyotrophic Lateral Sclerosis (ALS), a neurodegenerative disease that disproportionately affects glutamatergic and cholinergic motor neurons." (PMID 30296255, 2018). "Superoxide dismutase-1 (SOD1) mutants, including those with unaltered enzymatic activity, are known to cause amyotrophic lateral sclerosis (ALS)." (PMID 29703933, 2018). "Therefore, our results suggest that in some neurodegenerative diseases, like familiar amyotrophic lateral sclerosis (fALS), a gain of function due to mutated SOD1 could be ascribed to apoptosis mediated by raise of intracellular calcium concentration." (PMID 29881358, 2018). "Mutant Cu/Zn superoxide dismutase (SOD1) causes mitochondrial alterations that contribute to motor neuron demise in amyotrophic lateral sclerosis (ALS)." (PMID 30126943, 2018). "How SOD1 folds is of particular interest because its misfolding has been linked to amyotrophic lateral sclerosis (ALS), a fatal neurodegenerative disorder affecting motor neurons." (PMID 29192167, 2017). "In this review, we elucidate the role of metal binding in the aggregation process of copper-zinc superoxide dismutase (SOD1) associated to amyotrophic lateral sclerosis (ALS)." (PMID 28850080, 2017). "Dominant mutations in Cu/Zn-superoxide dismutase (SOD1) gene cause a familial form of amyotrophic lateral sclerosis (SOD1-ALS) with accumulation of misfolded SOD1 proteins as intracellular inclusions in spinal motor neurons." (PMID 28057013, 2017). "Mutations in the Cu/Zn-superoxide dismutase (SOD1) gene cause one form of familial amyotrophic lateral sclerosis (ALS), a progressive disorder of motor neurons leading to death." (PMID 26959009, 2016). "The human SOD1 gene (superoxide dismutase 1, synonym: Cu/Zn superoxide dismutase): its promoter contains a known SNP marker (rs7277748) of familial amyotrophic lateral sclerosis (ALS): this SNP causes overexpression of this gene." (PMID 28105927, 2016). "Superoxide Dismutase 1 mutants associate with 20–25% of familial Amyotrophic Lateral Sclerosis (ALS) cases, producing toxic aggregates on mitochondria, notably in spinal cord." (PMID 27721436, 2016). "This transgenic mouse line was originally developed in 1994 as a gene-dosage control for a mouse model of amyotrophic lateral sclerosis (ALS) overexpressing a SOD1-G93A mutation." (PMID 26823951, 2016). "SOD1 is a 150 amino-acid long protein whose mutations have been linked to familial Amyotrophic lateral sclerosis (ALS)." (PMID 27535545, 2016). "Furthermore, MITOL seems to be involved in the ubiquitination and degradation of misfolded proteins located in mitochondria, such as a mutated form of superoxide dismutase 1 (SOD1), an antioxidant enzyme that has been implicated in amyotrophic lateral sclerosis (ALS, or Lou Gehrig’s disease)." (PMID 26287188, 2015). "Approximately 20 % of cases of familial amyotrophic lateral sclerosis (ALS) are caused by mutations in the gene encoding Cu/Zn superoxide dismutase (SOD1)." (PMID 25404049, 2015). "However, alteration in wild type SOD1 expression or mutations in the gene have been held responsible for the activation of catabolic pathways associated with degenerative diseases, including amyotrophic lateral sclerosis (ALS)." (PMID 26491230, 2015). "Mutations in human SOD1 have been associated with amyotrophic lateral sclerosis (ALS), which is a fatal neurodegenerative disease." (PMID 25601439, 2015).
amyotrophic lateral sclerosis (continued). "Interestingly, superoxide dismutase-1 (SOD1) mutants that cause neurodegeneration in amyotrophic lateral sclerosis (ALS) have also been shown to inhibit ER-to-Golgi transport in neurons resulting in ER stress that can be ameliorated by over-expression of ER/Golgi vesicle machinery." (PMID 26617485, 2015). "Mutations in Cu/Zn superoxide dismutase (SOD1) are one of the genetic causes of Amyotrophic Lateral Sclerosis (ALS)." (PMID 26041991, 2015). "Mutations of the Superoxide Dismutase (SOD1) gene is behind 20% of cases of inherited amyotrophic lateral sclerosis (ALS)." (PMID 26793123, 2015). "Mutation of the superoxide dismutase 1 (SOD1) gene is the second most common cause of familial amyotrophic lateral sclerosis (ALS), a form of motor neuron disease." (PMID 24092880, 2014). "Mechanisms of human mutant superoxide dismutase 1 (SOD1)-induced toxicity in causing the familial form of amyotrophic lateral sclerosis (ALS) remain elusive." (PMID 25514244, 2014). "“Prion-like propagation” has recently been proposed for disease spread in Cu/Zn superoxide dismutase 1 (SOD1)-linked familial amyotrophic lateral sclerosis (ALS)." (PMID 25400549, 2014). "Dominant mutations in the Cu/Zn-superoxide dismutase (SOD1) cause familial forms of amyotrophic lateral sclerosis (ALS), a fatal disorder characterized by the progressive loss of motor neurons." (PMID 25054289, 2014). "Mutations in the superoxide dismutase gene (SOD1) are one cause of familial amyotrophic lateral sclerosis [ALS; also known as motor neuron disease (MND)] in humans." (PMID 24092880, 2014). "Mutations in superoxide dismutase 1 (SOD1) are a major cause of familial amyotrophic lateral sclerosis (ALS), whereby the mutant proteins misfold and aggregate to form intracellular inclusions." (PMID 24971881, 2014). "Mutations in the gene that encodes Cu/Zn-superoxide dismutase (SOD1) are the cause of approximately 20% of familial forms of amyotrophic lateral sclerosis (ALS), a fatal neurodegenerative disease characterized by the progressive loss of motor neurons." (PMID 25071458, 2014). "Mutations in the gene coding for superoxide dismutase 1 (SOD1) are associated with familiar forms of the neurodegenerative disease amyotrophic lateral sclerosis (ALS)." (PMID 24143259, 2013). "Mutations in the gene encoding human SOD1 (hSOD1) can cause amyotrophic lateral sclerosis (ALS) yet the mechanism by which mutant SOD1 can induce ALS is not fully understood." (PMID 23613814, 2013). "In amyotrophic lateral sclerosis (ALS), mutations within the ubiquitously expressed enzyme superoxide dismutase 1 (SOD1) gene are responsible for about a quarter of the inherited disease cases." (PMID 23734099, 2013). "It has been associated with other neurodegenerative diseases notably amyotrophic lateral sclerosis where mutations in human SOD1 account for ∼20% of familial ALS cases probably via a toxic gain of function." (PMID 23349894, 2013). "In the 20% of patients affected by an autosomal dominant form of amyotrophic lateral sclerosis (ALS), a gain of function mutation in SOD1 has been detected." (PMID 22792111, 2012). "To shed further light on these issues we examine here the cytotoxic response of cultured neuroblastoma cells to the metal-coordinating enzyme Cu/Zn superoxide dismutase (SOD1) implicated in the neurodegenerative disorder amyotrophic lateral sclerosis (ALS)." (PMID 22558346, 2012). "Transgenic rats expressing mutated superoxide dismutase 1 (hSOD1G93A) are classically used as a model for amyotrophic lateral sclerosis (ALS)." (PMID 21489258, 2011). "Amino acid replacements at dozens of positions in the dimeric protein human, Cu,Zn superoxide dismutase (SOD1) can cause amyotrophic lateral sclerosis (ALS)." (PMID 20404910, 2010).
amyotrophic lateral sclerosis (continued). "SOD1 gene mutations have been found in approximately 20% of individuals with the inherited form of amyotrophic lateral sclerosis (ALS) motor neuron disease (MND), a rapidly progressive and fatal neurological disorder." (PMID 21078175, 2010). "In animal models of amyotrophic lateral sclerosis (ALS), astrocytes expressing superoxide dismutase 1 (SOD1G93A) mutations display a neuroinflammatory phenotype and contribute to disease progression and motor neuron death." (PMID 20534165, 2010). "None of the cytokine mixtures had an effect on the gene for the mitochondrial protein Cu++/Zn++ SOD1; some familial forms of amyotrophic lateral sclerosis (ALS) are associated with mutations in this gene." (PMID 19159481, 2009). "We demonstrated that messenger RNA (mRNA) oxidation is a common feature in amyotrophic lateral sclerosis (ALS) patients as well as in many different transgenic mice expressing familial ALS-linked mutant copper-zinc superoxide dismutase (SOD1)." (PMID 18682740, 2008). "Mutations of the superoxide dismutase 1 (SOD1) gene are linked to amyotrophic lateral sclerosis (ALS), an invariably fatal neurological condition involving cortico-spinal degeneration." (PMID 18947433, 2008). "Death of motor neurons induced by an Amyotrophic Lateral Sclerosis (ALS)-linked Sod1 mutant is prevented by the Als2 gene product, alsin." (PMID 18769717, 2008). "Rilmenidine can significantly activate autophagy in neurons of a Huntington’s Disease mouse model and a mutant SOD1-induced amyotrophic lateral sclerosis mouse model." (PMID 40931164, 2026). "Glycation of superoxide dismutase 1 (SOD1) has been shown to modulate the cytosolic levels of phosphorylated TAR DNA-binding protein 43 (TDP-43), a hallmark of amyotrophic lateral sclerosis (ALS) pathology." (PMID 42074053, 2026). "These disorders include amyloid β (Aβ) for Alzheimer’s disease, superoxide dismutase 1 (SOD1) or Tar DNA binding protein-43 (TDP-43) for amyotrophic lateral sclerosis, and modified α-syn, such as nitrated or phosphorylated α-syn, for Parkinson’s disease." (PMID 40313365, 2025). "Amyotrophic lateral sclerosis (ALS) is a rare neurodegenerative disease prevalent in American and European populations, with its onset and progression significantly influenced by mutations in the superoxide dismutase 1 (SOD1) protein." (PMID 40050936, 2025). "Current knowledge about microglia's role in prion-like propagation of misfolded SOD1 in amyotrophic lateral sclerosis remains limited." (PMID 40046336, 2025). "Similarly, the overexpression of UBE3A increases the ubiquitination and facilitates the degradation of superoxide dismutase 1 (SOD1) proteins, which is linked to familial amyotrophic lateral sclerosis (ALS)." (PMID 40076922, 2025). "In amyotrophic lateral sclerosis (ALS), disrupted PINK1/Parkin signaling is associated with SOD1 and TDP-43 pathology." (PMID 40750884, 2025). "Therefore, mitochondrial malfunction and the formation of ROS, toxic to motor neurons in amyotrophic lateral sclerosis (ALS), are strongly associated with mutations in key genes, including SOD1." (PMID 40227270, 2025). "In amyotrophic lateral sclerosis (ALS), a specific mutation of superoxide dismutase 1 (SOD1) plays an important role, and downregulating mutant SOD1 (mSOD1) can slow ALS progression through reduced motor neuron (MN) damage and loss." (PMID 40843691, 2025). "Furthermore, connections with FUS, TARDBP, and NEFL, all linked to amyotrophic lateral sclerosis (ALS), highlight SOD1’s involvement in neurodegenerative disease pathways." (PMID 40710578, 2025). "Similarly, mutations in SOD1 associated with amyotrophic lateral sclerosis (ALS) share a similar molecular mechanism of dimer destabilization." (PMID 40244081, 2025). "The most extensively investigated relationship between SOD1 and human studies is amyotrophic lateral sclerosis (ALS), which is a late-onset severe motor-neuron degenerative disorder." (PMID 41154722, 2025).
amyotrophic lateral sclerosis (continued). "In addition, flavonoids were also shown to be protective against amyloid buildup in lethal conditions like Alzheimer's disease and amyotrophic lateral sclerosis (ALS) associated with SOD1 mutations." (PMID 41234634, 2025). "On the one hand, they help spread beta amyloid, tau, α-synuclein, TDP-43, and mutant SOD1, contributing to the signs and symptoms of Alzheimer’s, Parkinson’s, Amyotrophic lateral sclerosis, and Huntington’s Diseases." (PMID 41480618, 2025). "Box A ‐ dynamic and time‐averaged (static) resting state MEG metrics extracted from four participant groups: symptomatic amyotrophic lateral sclerosis (ALS), asymptomatic C9orf72 expansion carriers, asymptomatic SOD1 variant carriers, and healthy controls." (PMID 41042072, 2025). "Amyotrophic lateral sclerosis (ALS) is a neurodegenerative disease targeting motor neurons, and mutations in the gene encoding SOD1, as well as TDP-43 and FUS protein aggregates, have been reported to play a role in the development of ALS." (PMID 40549339, 2025). "In amyotrophic lateral sclerosis (ALS), familial cases are linked to mutations in the Cu, Zn superoxide dismutase (SOD1) gene, whereas sporadic cases demonstrate increased oxidative damage." (PMID 40214466, 2025). "Mutations in Sod1 are connected with amyotrophic lateral sclerosis (ALS)." (PMID 40157722, 2025). "SOD1 misfolding has been implicated in amyotrophic lateral sclerosis (ALS) disease." (PMID 39997105, 2025). "For example, in amyotrophic lateral sclerosis (ALS), a neurodegenerative disease affecting motor neurons, temperature-sensitive misfolding and aggregation of proteins such as superoxide dismutase 1 have been implicated in the disease pathogenesis." (PMID 41169496, 2025). "SOD1 mutations are a significant contributor of familial amyotrophic lateral sclerosis (ALS) cases." (PMID 40222103, 2025). "Amyotrophic lateral sclerosis (ALS) is a degenerative condition affecting the motor neurones, characterized by a multifaceted genetic makeup—mutations in genes such as SOD1, C9orf72, TARDBP, and FUS cause ALS." (PMID 39759457, 2024). "This same E2 Ube2k is up-regulated in the spinal cord of SOD1-G93A mice, a model of amyotrophic lateral sclerosis (ALS), another NDs." (PMID 39596581, 2024). "In amyotrophic lateral sclerosis (ALS), EVs are associated with TDP-43 fragments and SOD1 mutations." (PMID 38473976, 2024). "Mutations in SOD1 are associated with familial amyotrophic lateral sclerosis (ALS)." (PMID 39334768, 2024). "Growing evidence supports a role of chaperones in mediating such effects, as shown in mouse and fly models of Huntington’s disease or in SOD1 cellular models of amyotrophic lateral sclerosis (ALS)." (PMID 38507480, 2024). "Approximately 40–55% of amyotrophic lateral sclerosis (ALS) cases are attributed to mutations in over 50 identified ALS-associated genes; among these, pathogenic mutations in SOD1, C9ORF72, FUS, and TARDBP are the most prevalent." (PMID 38927671, 2024). "Amyotrophic lateral sclerosis (ALS) is associated with mutations in superoxide dismutase (SOD1) in motor neurons, excitotoxicity, defective axonal transport, oxidative damage, mitochondrial dysfunction, protein misfolding, abnormal cytoskeleton and neuroinflammation." (PMID 38318188, 2024). "Synthetic proteasome-activating peptide 1 (PAP-1) increased the ChT-L activity of the 20S and prevented the aggregation of superoxide dismutase 1 (SOD1) in a cellular model of amyotrophic lateral sclerosis." (PMID 38731881, 2024). "SOD1 has been extensively studied in neurological disorders such as Amyotrophic Lateral Sclerosis (ALS) and Parkinson’s disease, as well as cancer." (PMID 38316940, 2024). "The most frequently occurring SOD1 (Cu,Zn-SOD) mutation is D90A, which is responsible for Amyotrophic lateral sclerosis (ALS), a fatal neurodegenerative disease affecting motor neurons." (PMID 38483584, 2024).